FOXA1 (forkhead box A1)
Diseases named in the same sentence as FOXA1 in open-access papers (continued):
Sharing a sentence is not in itself a finding about the gene and the disease.
steatosis (7 papers, 2012 to 2024). Increased lipid within the cytoplasm of cells. "Various transcription factors associated with drug-induced steatosis share a common mechanism that involves the downregulation of Foxa1, Hex, and Srebp1c." (PMID 39061900, 2024). "While investigating the alterations of transcription factors in drug-induced steatosis, we noted a common pattern of downregulations of Foxa1, Hex, and Srebp1c." (PMID 39061900, 2024). "Forkhead box protein A1 (FoxA1) has been shown to protect liver from steatosis, which was down-regulated in NAFLD." (PMID 39277582, 2024). "This study concluded that the direct activation of GLP-1R by exendin-4 reduces steatosis in an in vitro model via stimulation of the Wnt/β-catenin signaling pathway and reduces FOXA1 expression and FABP1 expression, resulting in decreased FFA uptake." (PMID 37367037, 2023). "In conclusion, the present study proposes that the direct activation of GLP-1R by Ex-4 reduces OA-induced steatosis in HepG2 cells by stimulating the Wnt/β-catenin signaling pathway, which reduces FOXA1 expression." (PMID 35140289, 2022). "The increased expression of the pioneer factor FOXA1 in HepG2 cells and primary hepatocytes decreases Fatp2 expression along with lowered levels of fatty acid transport, thus protecting the liver from steatosis." (PMID 32188695, 2020). "The quantification of the fluorescence intensities in living cells once again revealed a significant inhibition of lipid accumulation by Foxa1, which reinforces the idea that this transcription factor can reduce steatosis in human liver cells." (PMID 22238690, 2012). "The quantification of accumulated lipids by Nile Red fluorescence demonstrated that Foxa1 significantly reduces steatosis in human hepatocytes and HepG2 cells." (PMID 22238690, 2012). "Thus, N800 treatment suppresses the expressions of transcription factors, including Foxa1, Srebp1c, and Pparα, and then induces hepatic MS, in line with the other types of drug-induced steatosis." (PMID 39061900, 2024). "Consistently, when Foxa1 levels are high, steatosis significantly lowers." (PMID 22238690, 2012). "Finally, we decided to know if the steatosis-induced repression of Foxa1 occurs in NAFL animal models." (PMID 22238690, 2012). "However, Foxa1 is down-regulated in human and rat NAFL and, therefore, increasing Foxa1 levels could protect from steatosis." (PMID 22238690, 2012). "To better understand the potential role of β-catenin as a molecular determinant through which Ex-4 mediates its beneficial effect on steatosis, we quantified the expression of FABP1, FOXA1, and ApoB after β-catenin silencing." (PMID 35140289, 2022).
urothelial carcinoma (7 papers, 2017 to 2026). A malignant neoplasm derived from the transitional epithelium of the urinary tract (urinary bladder, ureter, urethra, or renal pelvis). "One possible reason for this discrepancy might be the high percentage (41%) of histologic variants within the analyzed Mannheim cohort, which are often associated with poorer prognosis than pure urothelial carcinomas and demonstrate a higher expression of luminal markers such as FOXA1." (PMID 32252315, 2020). "The prognostic significance of the FOXA1 expression in urothelial carcinoma varies among different studies." (PMID 38425344, 2024). "In multivariable Cox regression analysis, OS was significantly correlated with the expression of CK14 (HR: 6.16, 95% CI: 1.28–38.30) and FOXA1 (HR: 0.08, 95% CI: 0.01–0.59) in the urothelial carcinoma subtype." (PMID 31500577, 2019). "Indeed, CK14 and FOXA1 expression may be a sensitive criterion for further differentiating urothelial carcinoma." (PMID 31500577, 2019).
diabetes (6 papers, 2012 to 2024). "In summary, the transcriptional regulators Foxa1 and Foxa2 share a significant fraction of cis-regulatory elements that contain a high-affinity forkhead binding site and regulate genes essential in development and those implicated in etiology of diabetes." (PMID 22737085, 2012). "Interestingly, Foxa1 and Foxa2 also occupy cis-regulatory elements of many diabetes susceptibility genes, both those mutated in MODY (mature onset diabetes of the young) and those with alleles associated with diabetes risk identified by genome-wide association studies (GWAS)." (PMID 22737085, 2012). "The newly identified diabetes-related gene, FOXA1 was highly amplified in ER+/PR+ (n = 3262) and ER+/PR− (n = 283) but not ER−/PR+ (n = 45) and ER−/PR− (n = 462)." (PMID 39000600, 2024). "We also performed several experiments to determine if the diabetes-related gene FOXA1 plays an important role in tumor cell growth and invasion in human HR+ BC cell lines." (PMID 39000600, 2024). "In summary, by incorporating functional information and conducting aggregated gene‐based testing, the most significant interactions we observed where between FOXA1 and BMI among men, and between PTPN2 and diabetes for CRC risk." (PMID 32207560, 2020). "The strongest association was for FOXA1 and BMI with CRC risk for men, and the predicted gene expression level of PTPN2 interacted with diabetes on CRC risk among men and women combined." (PMID 32207560, 2020). "In addition, we performed several experiments with the diabetes-related gene FOXA1 to assess its role in tumor cell growth and invasion in human HR+ BC cell lines." (PMID 39000600, 2024). "Because of the importance of pancreatic β-cells in diabetes, further understanding of the molecular regulatory pathways of FOXA1 and FOXA2 in pancreatic β-cell development and insulin secretion might provide therapeutic prospects." (PMID 38605023, 2024). "Three of the four TF found for the SB gene-TF network (NF-κB, FOXA1, and FOXD1) have been reported to be involved in (human) kidney disease and diabetes." (PMID 26830357, 2016). "FOXA1 and FOXA2 not only play a key role in organ development but also participate in the reprogramming of glucose and lipid metabolism, and they are targets for preventing and treating diabetes, fatty liver, obesity, cholestasis, and cancer." (PMID 38605023, 2024). "In summary, FOXA1 and FOXA2 control glucose metabolism by regulating multiple target genes in the pancreas, liver, and adipose tissue and are potential therapeutic targets for patients with diabetes." (PMID 38605023, 2024).
esophageal cancer (6 papers, 2011 to 2022). A primary or metastatic malignant neoplasm involving the esophagus. "Indeed, FoxA1 has been implicated as a tumor promoting factor and is upregulated in a subset of esophageal cancers as a result of genomic amplification." (PMID 21935353, 2011). "FoxA3 was also up-regulated and promoted metastasis in esophageal cancer cells through the regulations of FoxA1 and FoxA2 expressions." (PMID 32151057, 2020). "FoxA1, FoxA2 and FoxA3 play synergistic roles in metastasis of esophageal cancer." (PMID 32151057, 2020). "Abnormal expression of FOXA1 and FOXA2 has been observed in multiple types of cancers, including prostate, breast, lung, and esophageal cancer." (PMID 35897813, 2022).
Sepsis (6 papers, 2022 to 2025). Sepsis is defined as life-threatening organ dysfunction caused by a dysregulated host response to infection. "Sepsis-induced kidney injury-associated transcript 1 (SIKIAT1) is highly expressed in sepsis patients and lipopolysaccharide-stimulated HK-2 cells, and functions as a sponge for miRNA-96-3p to induce forkhead box A1 (FOXA1) expression and promote apoptosis." (PMID 40083322, 2025). "As expected, FOXA1 level was inversely associated with miR-338 in sepsis patients." (PMID 35148669, 2022). "Li and Gou found that FOXA1 was able to exacerbate LPS-induced vascular endothelial cell injury in sepsis by inhibiting NRP2 transcription, whereas silencing of FOXA1 reduced inflammatory factor." (PMID 39760528, 2025). "Berberine attenuated neonatal sepsis in mice by inducing miR-132-3p to inhibit FOXA1 and NF-κB signaling." (PMID 38180752, 2024). "Interestingly, FOXA1 is also involved in inflammatory processes in diseases, such as tumors, neuronal injury, and sepsis-induced kidney injury." (PMID 39760528, 2025). "We assumed that circHIPK3 might regulate forkhead box A1 (FOXA1) expression by sponging miR-338 in sepsis-induced AKI, thus providing a theoretical basis for the treatment of sepsis-induced AKI." (PMID 35148669, 2022). "In sum, our results elaborated that circHIPK3 knockdown attenuated LPS-triggered HK2 cell injury by regulating FOXA1 expression via interacting with miR-338, suggesting that circHIPK3 might be a potential biomarker and therapeutic target for sepsis-induced AKI patients." (PMID 35148669, 2022). "Our study demonstrated that circHIPK3 interference ameliorated apoptosis, inflammatory factors, and oxidative stress via the miR-338/FOXA1 axis in sepsis-induced AKI, suggesting that circHIPK3 might be a potential biomarker and therapeutic target for sepsis-induced AKI patients." (PMID 35148669, 2022).
asthma (5 papers, 2014 to 2023). "We focused on Epithelium-dominant TFs and found those encompassed by BEC-SEs have been previously implicated in lung development (FOXA1) and asthma, nasal polyposis, and mucociliary development (TP63, TP73)." (PMID 33362848, 2020). "Using DeepSEA, the moderate-to-severe asthma risk allele (G) at the sentinel SNP rs11603634 near MUC5AC was predicted to result in a log2 fold change of more than 1·5 in function at Forkhead Box A1 (FOXA1) and Forkhead Box A2 (FOXA2) binding sites in airway epithelium." (PMID 30552067, 2019). "Pathway cross-talk analysis highlights that signaling pathways mediated by IL-4/13 and transcription factor HIF-1α and FOXA1 play crucial roles in the pathogenesis of asthma." (PMID 31430856, 2019). "A meta-analysis study involving subjects with allergy and asthma identified the Chromosome 14q21.1 region and FOXA1 as candidates." (PMID 25111050, 2014). "Furthermore, the cross-talking of the IL-4/13 signaling pathway and networks intermediated by transcription factor HIF-1α and FOXA1 play a crucial role in the pathogenesis of asthma." (PMID 31430856, 2019). "As a result, they could be bonded asthma-related proteins, such as AR, FOXA1, GATA3, and GATA6." (PMID 37569643, 2023).
leukemia (5 papers, 2015 to 2022). A malignant (clonal) hematologic disorder, involving hematopoietic stem cells and characterized by the presence of primitive or atypical myeloid or lymphoid cells in the bone marrow and the blood. "The role of acetylation dynamics in FOXA1-mediated enhancer activation may be analogous to the recruitment of HDAC activity to leukemia-specific loci by the pioneer transcription factor PU.1." (PMID 35353838, 2022).
neuroendocrine tumors (5 papers, 2015 to 2026). "Compatible with key roles in the development of neuroendocrine tumors, MTC C cells differentially express the transcription factors Foxa1 and Foxa2, which are associated with tumor growth." (PMID 34208296, 2021). "FOXA2 mutations encode a transcription factor found in neuroendocrine tumors, MYC-N may promote the appearance of the NEPC phenotype, FOXA1 is downregulated in NEPC, and its absence in cell line models of PCa triggers neuroendocrine differentiation." (PMID 37569304, 2023). "Consistent with a key role in neuroendocrine tumor development, MTC cells differentially express transcription factors Foxa1 and Foxa2, correlating with tumor growth and invasion." (PMID 26395490, 2015).
Obesity (5 papers, 2012 to 2025). Accumulation of substantial excess body fat. "An example is the genomic locus of Fto (fat mass and obesity associated gene), where Foxa1 and Foxa2 bind four distinct intronic regions." (PMID 22737085, 2012). "We next considered whether the HVRs were enriched for either the occupancy of three specific transcription factors (HNF4A, CEBPA, and FOXA1) or the 418 rat orthologues of Human GWAS variants associated with obesity and metabolic traits." (PMID 29272997, 2017). "Overall, previous literature provides strong support for a potential role of FOXA1 in CRC which may be mediated through the FTO gene that could explain the observed interaction with obesity." (PMID 32207560, 2020). "This interaction may be explained by the observation that FOXA1 binds to four distinct intronic regions of the FTO (fat mass and obesity associated) gene, which has a known predisposing role to obesity." (PMID 32207560, 2020). "Obesity decreases the GLP-1 cell lineage as evidenced by lower NKX2.2, PAX6, FOXA1, and PDX1 gene expression in (Ob + ObD) individuals compared to NOb individuals." (PMID 33037328, 2021).
esophageal adenocarcinoma (4 papers, 2017 to 2020). A malignant tumor with glandular differentiation arising predominantly from Barrett mucosa in the lower third of the esophagus. "An oncogenic role of HNF3α (FOXA1) was observed in the progression and development of lung and esophageal adenocarcinoma." (PMID 33344262, 2020).
lung squamous cell carcinoma (4 papers, 2015 to 2022). "The analogy could also be extended to the lung squamous cell carcinoma subtype and suggests that downregulation of FOXA1 and GATA3 as well as upregulation/activation of EGFR and STAT3 as fundamental components of a generalized basal/squamous-like tumor phenotype." (PMID 26008846, 2015).
pulmonary fibrosis (4 papers, 2022 to 2024). Chronic progressive interstitial lung disorder characterized by the replacement of the lung tissue by connective tissue, leading to progressive dyspnea, respiratory failure, or right heart failure. "In our study, FOXA1 expression was suppressed in lung tissues of patients with pulmonary fibrosis and regulated the expression of EMT markers and the migration/invasion of fibroblast cells under hypoxia." (PMID 35804191, 2022). "In pulmonary fibrosis, H19 binds miR-29b, miR-423-5p, and miR-196a to silence the translation of Col1a1 (collagen, type I, alpha 1), Foxa1 (forkhead box A1), and COL1A1 mRNAs, respectively." (PMID 35893236, 2022). "Taken together, these results suggest that HDAC3 induces miR-224 expression to drive alveolar EMT through FOXA1 downregulation under hypoxic conditions, which may accelerate pulmonary fibrosis." (PMID 35804191, 2022). "Since fibroblast migration is considered a critical contributor to lung fibrosis, it was recently demonstrated that HDAC3-miR224- Forkhead Box A1 (FOXA1) axis effectively regulated the migration and invasion of fibroblast cells under hypoxia." (PMID 38474021, 2024). "Thus, it is reasonable to suggest that HDAC3 may accelerate pulmonary fibrosis progression under hypoxic conditions by enhancing EMT in alveolar cells through the regulation of miR-224 and FOXA1." (PMID 35804191, 2022).
type 2 diabetes (4 papers, 2014 to 2022). "We also show differential protein-DNA binding suggesting that the rs11257655 type 2 diabetes- risk allele increased transcriptional activity through binding a protein complex that includes FOXA1 and FOXA2." (PMID 25211022, 2014). "In the type 2 diabetes CDC123/CAMK1D GWAS (genome-wide association studies) locus, rs11257655 affects transcriptional activity by altering the binding of the protein complexes of FOXA1 and FOXA2, a potential molecular mechanism in type 2 diabetes." (PMID 35910194, 2022).
cholangiocarcinoma (3 papers, 2020 to 2025). A carcinoma that arises from the intrahepatic biliary tree (intrahepatic cholangiocarcinoma) or from the junction, or adjacent to the junction, of the right and left hepatic ducts (hilar cholangiocarcinoma). "Before-treatment and on-treatment biopsies were compared, revealing that mtIDH1 inhibition induced a more differentiated morphology of cholangiocarcinoma cells on H&E staining and the expression of hepatocyte lineage markers HNF-4α, FOXA1 (HNF-3α), FOXA2 (HNF-3β), and PPARA." (PMID 34967233, 2022).
diabetic nephropathy (3 papers, 2019 to 2025). "In diabetic nephropathy, its silencing attenuates podocyte injury and apoptosis through a FOXA1-dependent axis." (PMID 41303683, 2025).
endometrial tumors (3 papers, 2014 to 2019). "The same was observed when comparing FOXA1 levels in metastases from only ERα positive primary endometrial tumors (r2 = 0.11)." (PMID 24849812, 2014). "Therefore, in CTCF haploinsufficient endometrial tumours, FOXA1/ER interactions with chromatin may increase leading to upregulation of estrogen-responsive genes." (PMID 30513694, 2018).
Hyperglycemia (3 papers, 2020 to 2024). An increased concentration of glucose in the blood. "Studies have shown that mice deficient in FOXA1 in the pancreas exhibit hyperglycemia." (PMID 38605023, 2024). "In contrast to normal mice, FOXA1- and FOXA2-deficient mice exhibit hyperglycemia and die shortly after birth." (PMID 38605023, 2024). "Apart from IGFBP-2, an increase in the level of FOXA1 by hyperglycaemia in prostate cell lines was also observed in this study." (PMID 32655839, 2020). "IGF-I and hyperglycaemia-induced FOXA1/IGFBP-2 play important roles in EMT." (PMID 32655839, 2020). "We also investigated the potential mechanism that mediated the effect of hyperglycaemia on EMT by assessing the role of IGFBP-2 and FOXA1." (PMID 32655839, 2020). "Alternatively, the absence of FOXA1 may affect the development and maturation of pancreatic β-cells, inhibiting insulin secretion and leading to hyperglycemia." (PMID 38605023, 2024).
Hypoglycemia (3 papers, 2023 to 2025). A decreased concentration of glucose in the blood. "This phenomenon suggests that α cells of FOXA1-deficient mice lose the ability to respond to hypoglycemia by increasing glucagon secretion." (PMID 36798663, 2023). "Initial interest in the role of Foxa1 in pancreatic disease arose from observations of hypoglycemia and abnormal changes in glucose metabolism in Foxa1 knockout mice." (PMID 39707176, 2024).
invasive lobular carcinomas (3 papers, 2017 to 2020). "Genetic analysis of invasive lobular carcinomas, which were predominantly categorized as the luminal A subtype, exhibited recurrent FOXA1 mutations and correlation with high FOXA1 activity." (PMID 29137314, 2017). "Recently, molecular analyses of invasive lobular carcinomas established that these tumors have a distinct genomic profile compared to IBC-NST, exhibiting a high frequency of CDH1 mutations, loss of PTEN, activation of AKT, and mutations in TBX3 and FOXA1." (PMID 32487046, 2020).
liver fibrosis (3 papers, 2021 to 2024). "This study indicated that the elevated expression of FOXA1 is linked to a better prognosis in individuals with HCV-induced early liver fibrosis." (PMID 38287425, 2024). "The mechanism of CBS, CYP1A2, FOXA1, GSTZ1, WDR72 and UHMK1 in the progression of liver fibrosis is still unclear." (PMID 38287425, 2024). "According to the validation of clinical specimens, CBS, CYP1A2, FOXA1, GSTZ1, WDR72 and UHMK1 were specifically expressed in patients with liver fibrosis or hepatocirrhosis." (PMID 38287425, 2024). "Together, these results identified an important regulatory axis whereby LINC00663 that was regulated by FOXA1 sponged hsa-miR-3916 and regulated SF2-FN alternative splicing expression in cholestatic liver fibrosis." (PMID 36672150, 2023). "The downregulated genes in liver fibrosis tissues were Aox4, CYP2C11, Mup5, Loc100912565, Loc100909412, Loc100360095, Loc259244, Cat, Crp, and Foxa1." (PMID 34597331, 2021).
melanoma (3 papers, 2016 to 2021). A malignant, usually aggressive tumor composed of atypical, neoplastic melanocytes. "Of the cellular populations tested, the eight BCa cell lines expressing FoxA1 or FoxA2 had very high levels of LIPG protein compared with the melanoma MDA435 cell line and the human epithelial cell." (PMID 27045898, 2016). "We compared FoxA1 and FoxA2 mRNA expression in four estrogen receptor positive (ER+) (MCF7, T47D, BT474 and ZR75) and four estrogen receptor negative (ER−) (SKBR3, MDA468, BT20 and MDA231) BCa cell lines, a cell line of melanoma origin (MDA435), and human mammary epithelial cells (HMECs)." (PMID 27045898, 2016).